LGALS1 (galectin 1)
Diseases named in the same sentence as LGALS1 in open-access papers (continued):
Sharing a sentence is not in itself a finding about the gene and the disease.
tumor (continued). "Galectin-1, -3 and -9 are three well-investigated galectins which can modulate tumor cells growth and regulate immune cells." (PMID 29389859, 2018). "The tumor material of 43 patients of the LUMC cohort was available to perform galectin-1 immunohistochemistry staining." (PMID 30140386, 2018). "The TF LP or RGD LP delivery systems, αvβ3, and galectin-1 with paramagnetic Anx/RGD-liposomes have been used for tumor imaging." (PMID 30483904, 2018). "It has been described that galectin-1 is upregulated in different tumors, promoting the tumor immune scape, promoting T cell apoptosis, angiogenesis, and transformation." (PMID 29410666, 2018). "Galectin-1 is expressed and released by different cell types and exerts biological functions at different levels of tumor progression." (PMID 30140386, 2018). "Our previous studies show that galectin-1 over-expression in tumor cells is correlated with tumor stages, grades, and invasion." (PMID 29671787, 2018). "An in-depth comparison analysis demonstrated that mice reconstituted with Lgals1-/- lymphocytes showed a marked increase in tumor latency and a slight decrease in tumor duplication time." (PMID 30319642, 2018). "The present study showed that galectin-1 was expressed by CAFs, immune, endothelial and tumor cells at different intensities." (PMID 30140386, 2018). "Previously, it has been reported that several tumor cells lose their tumorigenicity when injected into Lgals1-/- mice, compared with their injection into wild-type mice." (PMID 30319642, 2018). "Galectin-1 (Gal-1) has been described to promote tumour growth by inducing angiogenesis and to contribute to the tumour immune escape." (PMID 29498681, 2018). "This suggests that upregulated galectin-1 expression in stroma-high tumors provides a microenvironment characterized by immune suppressive response resulting in invasive tumor cells." (PMID 30140386, 2018). "This system allowed us to compare the ability of Lgals1-/- and wild-type lymphocytes to control tumor growth in a WT micro- and macro-environment." (PMID 30319642, 2018). "Targeted inhibition of galectin-1 is correlated with enhanced T cell-mediated tumor clearance, demonstrating a strong immunosuppressive effect on T cells." (PMID 29389859, 2018). "Results of cohort studies showed that galectin-1 expression in biopsy samples was significantly correlated with the primary tumor (pT) status, grade, nodal metastasis, vascular invasion, perineural invasion, and mitotic rate." (PMID 29671787, 2018). "During tumor progression, stromal cells, in particular CAFs, increase galectin-1 secretion which suppresses the immune response and is involved in tumor invasion." (PMID 30140386, 2018). "Specifically, galectin-1 is a possible independent prognostic marker of urothelial carcinoma, with its positive immuno-expression being significantly correlated with tumour stage, grade, vascular invasion and nodal status." (PMID 29207682, 2017). "Galectin-1 inhibitor OTX008 transiently increased overall tumor oxygenation via vessel normalization to various degrees in both HNSCC models." (PMID 29232825, 2017). "Both Galectin-1 and Galectin-3 are located in the extracellular space and have similar functions, such as lattice formation and regulation of tumour adhesion, invasion and migration." (PMID 28701735, 2017). "We found Galectin-1 overexpressing PSCs significantly promoted tumor growth, while Galectin-1 knockdown PSCs reduced the tumor size compared to the control mice (p < 0.05)." (PMID 29156810, 2017). "We observed that detachment from monolayer culture and growth as tumor spheroids was accompanied by changes in glucose metabolism, endogenous ROS levels, galectin-1 and glucose transporter GLUT1 protein levels." (PMID 28545086, 2017).
tumor (continued). "Using a Wilcoxon test, the expression of galectin-1 and integrin α5β1 in tumor cells was significantly decreased in postchemotherapy samples compared with prechemotherapy tissue samples, respectively (P<0.05)." (PMID 28842515, 2017). "Galectin-1 and integrin α5β1-positive immunostaining was more frequently observed in stromal cells than its in tumor cells." (PMID 28842515, 2017). "There is a positive association between galectin-1 expression and PDAC tumor size, lymph node metastasis, perineural invasion, differentiation, Union for International Cancer Control stage, and survival." (PMID 29254283, 2017). "Conversely, galectin-1 has been implicated in the promotion of cancer cell immune evasion, and blockade of tumor-derived galectin-1 promotes tumor rejection via the augmentation of pro-inflammatory T cell responses." (PMID 29075269, 2017). "Our mixed (PSCs and PANC-1 cells) mouse orthotopic xenograft model indicated that overexpression of Galectin-1 in PSCs significantly promoted the proliferation, growth, invasion, and liver metastasis of the transplanted tumor." (PMID 29156810, 2017). "In this study, we evaluated the consequences of reducing Galectin-1 (Gal-1) in the tumor micro-environment (TME) of glioblastoma multiforme (GBM), via nose-to-brain transport." (PMID 28450700, 2017). "In both models, galectin-1 inhibition in MM cells significantly reduces tumor masses, tumor angiogenesis, and, in the intratibial model, the formation of bone lesions." (PMID 29258207, 2017). "In the TME, persistent PSC activation promotes tumor cell malignant behavior, and galectin-1 plays a crucial role in PSC activation." (PMID 29254283, 2017). "Together these findings indicate Galectin-1 is involved in PSCs cross-talk in PDAC, and provide a preclinical rationale for targeting Galectin-1 as a tumor microenvironment-based therapeutic strategy." (PMID 29156810, 2017). "Galectin-1 was also recently shown to promote tumor progression through upregulation of CXCR4 via activation of the NF-κB pathway." (PMID 29156810, 2017). "Together, these data suggest a role for galectin-1 in the induction of Ts-phenotype and functional changes by tumor-derived exosomes." (PMID 28806909, 2017). "The expression of galectin-1 and integrin α5β1 in tumor cells and stromal cells was analyzed by immunohistochemistry." (PMID 28842515, 2017). "Together, these results indicate PSC-derived Galectin-1 promotes tumor establishment, growth, and metastasis." (PMID 29156810, 2017). "Galectin-1 is a β-galactoside-binding protein that is abundantly secreted by almost all the types of malignant tumor cells." (PMID 28842515, 2017). "In particular, Galectin-1 (which is highly expressed in PSCs in PDAC) plays a key role in this desmoplastic reaction, with elevated Galectin-1 expression highly correlated to tumor histology, stage, and poor prognosis." (PMID 29156810, 2017). "Nevertheless, our results indicated that HSC-derived galectin-1 correlated with tumor immune privilege and HCC progression." (PMID 27494859, 2016). "While galectin-1 has been observed to enhance tumor-induced angiogenic processes, the mechanisms of action have not been fully resolved." (PMID 27649167, 2016). "For example, galectin-1 has been found to arbitrate cellular aggregation, migration and invasion, tumor-induced angiogenesis, and T cell apoptosis." (PMID 27649167, 2016). "Our recent studies demonstrate targeting of irradiated tumor endothelial cells via radiation-induced stromal enrichment of Galectin-1 using Anginex conjugated liposomes encapsulating ATO and cisplatin." (PMID 27223428, 2016). "In galectin-1 knockout experiments using mice, impedance of tumor growth due to inadequate angiogenesis has been observed." (PMID 27649167, 2016). "In support of the role of galectin-1 in tumor immunosuppression, in vivo blockage of galectin-1 expression in tumor cells of syngeneic mice promoted tumor rejection and stimulated tumor-specific T cell-mediated responses." (PMID 27649167, 2016).
tumor (continued). "Upon subsequent treatment with galectin-1 sufficient tumors, the syngeneic mice exhibited an enhanced tumor immune response by resisting tumor challenge." (PMID 27649167, 2016). "Initially, galectin-1 multivalently mediates tumor cell–ECM adhesion at the primary site by cross-linking cell surface glycoproteins, such as integrins, and glycosylated proteins in the ECM, such as laminin and fibronectin." (PMID 27649167, 2016). "Galectin-1 mechanisms in cellular aggregation/tumor formation, migration and invasion, tumor-induced angiogenesis, and apoptosis of activated T cells are discussed in detail in the following sections of this review." (PMID 27649167, 2016). "Statistical evaluation of the immunohistochemistry revealed significantly increased expression of galectin-1 in tumor tissues as compared to the normal breast tissues." (PMID 27223428, 2016). "The increased expression of galectin-1 has been correlated with a variety of processes in cancer progression, including the cellular aggregation/tumor formation, metastatic spread of cancer, angiogenesis, and apoptosis." (PMID 27649167, 2016). "DEspR and Galectin-1 are indeed co-localized in tumors, and located more in the expanding tumor zone." (PMID 27301377, 2016). "Using the same murine TNBC model in this study we compare the galectin-1 expression between benign breast, tumor and irradiated tumor tissue originating from TTA implants in the mammary fat pad of nude mice." (PMID 27223428, 2016). "Multivalent interactions involving galectin-1 in cellular adhesion, mobility and invasion, tumor-induced angiogenesis, and apoptosis are presented." (PMID 27649167, 2016). "Galectin-1, for example, is a multivalent carbohydrate binding protein that mediates the malignant cellular activities by cross-linking glycoproteins in the tumor microenvironment." (PMID 27649167, 2016). "Binding of galectin-1 to trophoblast tumor cells presenting the oncofetal Thomsen-Friedenreich (TF) carbohydrate antigen inhibits tumor cell proliferation." (PMID 27825375, 2016). "Studies, including our own, have demonstrated the potential of galectin-1 as a therapeutic target by identifying the overexpression of galectin-1 in various human cancers and enrichment in tumor stroma." (PMID 27223428, 2016). "The binding of cell-surface glycoproteins, such 90K/Mac-2BP and Mucin 1, by galectin-1 mediates cellular aggregation/tumor formation." (PMID 27649167, 2016). "These abundantly secreted galectin-1 proteins are considered to promote tumor cell migration, invasion and metastasis." (PMID 26859293, 2016). "Accumulating evidences have demonstrated that galectin-1 is closely relevant to the tumor progression by promoting transformation, angiogenesis, and metastasis." (PMID 27050374, 2016). "Once the tumor cell migrates to and invades a secondary site, galectin-1 mediates adhesion by cross-linking tumor cells with the ECM." (PMID 27649167, 2016). "Studies using animal models support the critical role of galectin-1 in mediating tumor growth and metastasis." (PMID 27649167, 2016). "A carbohydrate binding protein, galectin-1, which plays a pivotal role in tumor growth and cancer progression including invasion, angiogenesis and metastasis is a propitious alternative for stromal targeting of the non-transformed tumor associated-endothelium." (PMID 27223428, 2016). "The glycodendrimers inhibited cellular aggregation by providing competitive binding sites for the galectin-1 and diverting the galectin-1 from its native role in cellular cross-linking, which leads to cellular aggregation/tumor formation." (PMID 26124876, 2015). "If this was the case, galectin-3 was mainly expressed in the center of the tumor fields, while galectin-1 and -9 were expressed at the invasive border." (PMID 26066796, 2015).
tumor (continued). "Galectin-1 is constitutively expressed in immune privileged sites such as the eye, testes, and placenta, and galectin-1 expression by tumor cells has been shown to dampen the anti-tumor effect of infiltrating CD8 T cells." (PMID 26216879, 2015). "Albeit LGALS9 has not yet been implicated in NSCLC or in a chemotherapy-refractory phenotype of other tumor cells, various galectins such as galectin-1 and -3 were reported to have a role in driving a chemotherapy-refractory phenotype." (PMID 26353782, 2015). "Triple positive cells were strongly correlated with galectin-1/9 double positive cells within the tumor epithelium (R = 0.682, p<0.0001)." (PMID 26066796, 2015). "To further the mechanistic understanding of multivalent galectin-1 in biological processes such as cellular aggregation/tumor formation, we applied lactose functionalized poly(amidoamine) (PAMAM) dendrimers as a multivalent framework." (PMID 26124876, 2015). "DU145 cells express elevated levels of both galectin-1 and its putative receptor Mucin-1, which suggests that galectin-1 mediated β-galactoside binding is critical to cellular aggregation/tumor formation in this cell line." (PMID 26124876, 2015). "Compared with the levels in 70 healthy individuals, only about 37 % of examined EOC cases showed galectin-1 concentration more than the cutoff level; however, the incidence of supernormal levels of galectin-1 was elevated in relation to tumor progression." (PMID 26589590, 2015). "Galectin-3 single positive cells were strongly correlated with galectin-1/3 double positive cells within the tumor stroma (R = 0.693, p<0.0001)." (PMID 26066796, 2015). "In tumor cells, galectin-3 expression often appeared mutually exclusive with expression of galectin-1 or -9, since its expression was reduced when expression of another type of galectin was present." (PMID 26066796, 2015). "Patients with strong tumor cell galectin-1 expression had increased tumor invasion and received post-operative radiotherapy treatment more frequently." (PMID 26066796, 2015). "Many galectins including galectin-1 and galectin-3 have also shown a correlation with tumor development and can be used as markers of potential cancerous growth." (PMID 25730388, 2015). "Correspondingly, galectin-1 selectively secreted by tumor-derived γδ T cells was sufficient to promote accelerated tumor growth." (PMID 25897427, 2015). "According to our results, that removal of the tumor decreased serum galectin-1 concentrations, tumor tissues are likely to produce and secrete galectin-1 in sera." (PMID 26589590, 2015). "More studies are warranted to determine the clinical value of circulating galectin-1 in patients with early-stage cancer as a predictor of tumor invasion and metastasis." (PMID 26589590, 2015). "Our work demonstrates that bulk populations of γδ T cells in human and mouse tumors secrete more immunosuppressive galectin-1 on a per cell basis than any other cell type in the tumor microenvironment." (PMID 25897427, 2015). "The hazard ratio for disease-specific survival in case of strong galectin-1 tumor expression was 8.9 (95% CI: 2.961–26.717)." (PMID 26066796, 2015). "The results showed that galectin-1 knockdown significantly suppressed growth of xenografts in SCID mice as well as the tumor weights at the end of studies." (PMID 25605013, 2015). "Expanded MDSCs in turn influence γδ T cells to secrete immunosuppressive galectin-1, which abrogates anti-tumor immunity and accelerates malignant progression." (PMID 25897427, 2015). "Strong expression of galectin-1 by tumor cells was significantly correlated with poor disease-free (p = 0.0004) and disease-specific survival (p<0.0001)." (PMID 26066796, 2015). "Galectin-1 (gal-1), a member of the β-galactoside-binding protein family, is a multifunctional protein capable of regulating multiple processes such as tumor cell adhesion, proliferation, differentiation, apoptosis, invasiveness and metastasis." (PMID 25605013, 2015).
tumor (continued). "In fact, galectin-1-knock out mice showed insufficient tumor angiogenesis during tumor growth in vivo." (PMID 26413750, 2015). "Most galectin-1 expressing cells infiltrating in the tumor epithelium were macrophages, predominantly CD163+ type 2 macrophages." (PMID 26066796, 2015). "In our current study, we demonstrated that LYAR directly binds to the LGALS1 gene promoter at −1359 bp to induce galectin-1 expression and to promote tumor invasion and the migration of CRC cells." (PMID 26413750, 2015). "As blocking galectin-1 expression has already been shown to inhibit tumor angiogenesis and induce T cell dependent tumor rejection in mice, our data support further studies of the therapeutic potential of targeting galectin-1 in positive tumors." (PMID 26066796, 2015). "Tumor cell galectin-1 expression was also correlated with increased tumor invasion depth (p = 0.032)." (PMID 26066796, 2015). "Of most relevance to the present study are experimental observations to link the dysregulation of galectin-1 expression to the invasion and metastasis formation of cancer cells, promote tumor angiogenesis and protect tumors from host immune responses." (PMID 26589590, 2015). "Tumor galectin-1 intensity was also an independent predictor of poor disease-free survival (hazard ratio: 3.41, 95% CI: 1.296–8.972, p = 0.013)." (PMID 26066796, 2015). "Galectin-1 and -9 were both expressed by tumor cells in 11% of samples, while 84% expressed galectin-3." (PMID 26066796, 2015). "Galectin-1 and -3 were most likely co-expressed by tumor epithelium infiltrating type 2 macrophages." (PMID 26066796, 2015). "Galectin-1 has been described to be infrequently expressed by tumor cells, which was confirmed by the current study." (PMID 26066796, 2015). "In different cancer models, galectin-1 has been demonstrated to play a pivotal role in tumor-mediated immune evasion especially by modulating cells of the adaptive immune system." (PMID 26137448, 2015). "Strong galectin-1 expression by tumor cells was an independent predictor for poor survival (hazard ratio: 8.02, p = 0.001) and correlated with increased tumor invasion (p = 0.032) and receiving post-operative radiotherapy (p = 0.020)." (PMID 26066796, 2015). "We examined galectin-1 expression in EOC tumor samples by Western Blot, qRT-PCR and immunohistochemistry." (PMID 26589590, 2015). "Immunohistochemical assessment of galectin-1 and galectin-9 protein expression showed differences in the localization and distribution within the tumor tissue." (PMID 25259711, 2014). "Distances between tumor cells (positivity for galectin-8 at high intensity) and lymphocytes as well as between galectin-1-positive tumor cells were of prognostic relevance in testicular cancer patients with lung metastases." (PMID 24443956, 2014). "Galectin-1 and gangliosides, overexpressed and actively shedded by tumor cells, can modulate normal cells present in the tumor microenvironment, favoring angiogenesis and immunological escape." (PMID 24904828, 2014). "Subsequent Pearson correlation analysis of the staining scores showed that there was a significant inverse correlation between the score of galectin-1 and galectin-9 in the tumor cells (corr." (PMID 25259711, 2014). "Previously some reports show that galectin-1 can induce apoptosis in T cells and tumor galectin-1 suppresses T cell immunity through induction of apoptosis of T cells." (PMID 24589677, 2014). "Galectin-1 acts as extracellular matrix as well as a modulator of cell adhesion and invasion to extracellular matrix in tumor cell lines." (PMID 24589677, 2014). "Taken together, tumor-derived Galectin-1 exerts its immunosuppressive function through binding to endogenous (non-tumor-derived) glycans and thereby contributes to cancer progression." (PMID 24592356, 2014).